IL13 (interleukin 13)
Diseases named in the same sentence as IL13 in open-access papers (continued):
Sharing a sentence is not in itself a finding about the gene and the disease.
colitis (continued). "To address the role that IL-4/IL-13 signalling plays on macrophages in oxazolone-induced colitis, we used the macrophage/neutrophil-specific IL-4Rα-deficient mouse strain (LysMcreIL-4Rα-/lox)." (PMID 32410852, 2020). "Combined, our data suggests that IL-4/IL-13 signalling on intestinal epithelial cells, smooth muscle cells, macrophages, and neutrophils plays a redundant role in oxazolone colitis." (PMID 32410852, 2020). "A study using oxazolone to induce colitis in mice recently demonstrated that expression of IL-13 was enhanced in ILC2s in response to IL-25." (PMID 30999584, 2019). "IL-33 is a well-known regulator of mucin responses in multiple inflammatory settings, but our colitis model largely found IL-13- and IL-22-dependent signaling." (PMID 30518915, 2018). "In a mouse model of T cell-induced colitis, GM-CSF increased the production of IL-4, IL-10, and IL-13 and decreased the production of interferon gamma (IFN-γ) in lamina propria mononuclear cells." (PMID 29703251, 2018). "Increasing evidence demonstrates that IL-13 is responsible for initiating the detrimental inflammatory cascade in colitis." (PMID 30460209, 2018). "In the sedentary group fed a SD, the plasma TNF-α, MCP-1, IL-6 and IL-13 were negligible but in the mice with colitis, a significant increase in the plasma levels of these cytokines was observed (p < 0.05)." (PMID 28425943, 2017). "In the oxazalone-induced colitis model, iNKT cells were induced to produce IL-13 by bone-marrow-derived cells." (PMID 29375569, 2017). "In contrast, such an elevation in the plasma levels of TNF-α, MCP-1, IL-6 and IL-13 was significantly attenuated in the HFD mice subjected to voluntary exercise prior to the induction of colitis (p < 0.05)." (PMID 28425943, 2017). "Studies also show that mesenteric lymph node cells from STAT6 (−/−) mice with colitis exhibited reduced secretion of IL-4, IL-13, and IFN-γ." (PMID 28752100, 2017). "In fact, an increase in cytokines, including the ‘cytokine triumvirate’ of TNF-α, IL-6 and IL-13, has been recently proposed to play a role in the progression of experimental colitis and human IBD." (PMID 28425943, 2017). "Murine infection with S. mansoni prevents colitis in a macrophage-dependent but IL-4- and IL-13–independent manner, representing another population of suppressive macrophages." (PMID 27101372, 2016). "Histological severity of murine colitis peaked on day 1, accompanied by an increase in the expression of Th2 cytokines including IL-4 and IL-13." (PMID 27966619, 2016). "Regarding expression of cytokines involved in epithelial cell dysregulation and damage, intestinal eosinophils expressed higher amounts of Tnf, Il6, and Il13 mRNA in colitis compared to uninflamed controls." (PMID 26200014, 2015). "Confirmatively, antagonism of IL-13 is effective to prevent fibrosis development in experimental colitis." (PMID 24678903, 2014). "IL-13 appears to also play a role in the pathogenesis of IBD especially UC, since levels of IL-13 were increased in patients with UC and blockage of IL-13 was effective in treatment of murine colitis induced by oxazolone." (PMID 25937893, 2014). "In the murine model of 2,4,6-trinitrobenzene sulfonic acid (TNBS)-induced colitis, inhibition of IL-13 signaling by administration of small interfering RNA targeting the IL-13-α2 receptor attenuated inflammation-associated intestinal fibrosis." (PMID 24678903, 2014). "This study is the first to report an important role of IL-13 in generation of inflammation in two different experimental models (DSS and DNBS) of colitis and also identifies 5-HT as a vital factor in pathogenesis of IL-13-mediated colitis." (PMID 24015275, 2013). "IL-13−/− mice administered DSS exhibited significantly reduced severity of colitis compared to WT mice as reflected by macroscopic and histological damage assessments." (PMID 24015275, 2013).
colitis (continued). "This became evident when severity of colitis in IL-13−/− mice increased following enhancement of colonic 5-HT amount via 5-HTP treatment, which was also marked by the increased production of pro-inflammatory cytokines." (PMID 24015275, 2013). "A significant increase in colonic 5-HT content was observed in IL-13−/− mice receiving 5-HTP compared to IL-13−/− receiving vehicle following induction of DSS colitis." (PMID 24015275, 2013). "Reduction in the severity of DSS colitis was associated with significantly lower MPO activity, as well as reduced IL-1β, IL-6 and IL-17 production in IL-13−/− mice." (PMID 24015275, 2013). "Along with increased severity of colitis, a significant increase in 5-HT expressing EC cell numbers and 5-HT production was observed in the IL-13−/− mice receiving rmIL-13 compared to IL-13−/− mice receiving vehicle." (PMID 24015275, 2013). "Post-mortem macroscopic assessment and histopathological evaluation also revealed significant enhancement of severity of colitis in IL-13−/− mice that received 5-HTP as compared to the IL-13−/− mice that received vehicle." (PMID 24015275, 2013). "In this study, significantly reduced 5-HT expressing EC cell numbers were observed in IL-13−/− mice following induction of DSS colitis compared to WT mice." (PMID 24015275, 2013). "The reduced severity of colitis observed in IL-13−/− mice was also accompanied by down-regulation of EC cell numbers and colonic 5-HT content." (PMID 24015275, 2013). "To confirm the effects of IL-13 in 5-HT production and in turn severity of colitis, we reconstituted IL-13−/− mice with rmIL-13." (PMID 24015275, 2013). "In this study, we investigated the role of IL-13 mediated 5-HT signaling in pathogenesis of colitis." (PMID 24015275, 2013). "In the current study, using two different models of experimental colitis, we identified 5-HT as an important arbitrator of IL-13-mediated gut inflammation." (PMID 24015275, 2013). "We found that in oxazolone colitis IL-25 production derives from intestinal epithelial cells and that IL-17BR+ IL-13-producing natural killer T (NKT) cells and nuocytes drive the intestinal inflammation." (PMID 22539101, 2012). "IL-13, which is produced by both Th2 and NK T cells, has been shown to play a fundamental role in the pathogenesis of colitis and can be inhibited by Type I IFN." (PMID 21365015, 2011). "In colitis mice, TA administration increased IL-13 and IL-5Rα levels compared to those in untreated colitis mice, suggesting that TA may exacerbate colitis symptoms." (PMID 40333150, 2025). "Furthermore, the association between increased IL-13 and IFN-γ levels and TJ disruption, contributing to barrier impairment in colitis, is well-documented." (PMID 39650157, 2024). "In harmony with previous studies, our results showed significant up-regulation of NFATC1 expression with higher histopathological scores in mice with oxazolone-induced colitis, in addition to the induced extensive inflammatory response evidenced by enhanced IL-13 production." (PMID 37902927, 2024). "IL-13 and IL-4 can prompt intestinal fibrosis by down-regulating matrix metalloproteinase synthesis in fibroblasts, which has led to collagen accumulation in the intestinal tissue of in vitro and in vivo experimental models of CD and colitis." (PMID 38058517, 2023). "Moreover, IL-13 plays a critical role in the pathogenesis of experimental colitis, and ECs-derived 5-HT is an important mediator of IL-13 driven intestinal inflammation." (PMID 35370559, 2022). "Oxazolone appears to be an interesting chemical agent for modeling UC-like colitis, even if this colitis was shown to be essentially dependent on Interleukin-13-producing NKT cells, certainly involved in the pathophysiology of UC, but without being the only ones." (PMID 36560599, 2022). "Colitis can activate Th1 cells, resulting in the release of Th1-related cytokines such as IFN-γ, while ulcerative colitis is associated with Th2 and the release of IL-5, IL-13, and IL-9." (PMID 35240996, 2022).
colitis (continued). "Blocking the IL-13/STAT6 signaling pathway alleviated colitis in WRS and DEX-injected mice." (PMID 36032134, 2022). "Notably, IL-5 and IL-13 were mainly secreted by CD45+Lin−GATA3+ cells in the colon of Oxa-induced colitis, suggesting that ILC2s were the main producers of type 2 cytokines rather than Th2 cells." (PMID 35116024, 2021). "Owing to Oxa-induced colitis being mediated by type 2 immunity, the effect of melatonin on the secretion of type 2 inflammatory cytokines was assessed, and melatonin treatment markedly suppressed the production of IL-5 and IL-13 in the colon of the MT50 group." (PMID 35116024, 2021). "Therefore, the epithelial cell-specific IL-4Rα-deficient mouse strain would be able to directly test the effect of IL-13 signalling on epithelial cells and disease onset in oxazolone colitis." (PMID 32410852, 2020). "Data from a study focusing on spontaneous resolution of inflammation in a murine trinitrobenzene sulfonic acid-induced colitis model revealed that colitis-induced secretion of IL-13 led to the inactivation (i.e., Ser9 phosphorylation) of GSK3β via the STAT6-driven activation of p38." (PMID 32231133, 2020). "We also measured Il-4 and Il-13 mRNA expression in the colonic tissues of normal and colitis mice." (PMID 33192516, 2020). "Hence, the smooth muscle cell-specific IL-4Rα-deficient mouse strain provided us with a tool to understand the role of IL-4/IL-13-reponsive smooth muscle cells in oxazolone colitis." (PMID 32410852, 2020). "Therefore, the IL-4Rα-expressing cell type responsible for the regulation of IL-4/IL-13 signalling during oxazolone colitis remains to be determined." (PMID 32410852, 2020). "Finally, another study revealed that GATA3 transgenic mice exhibited more pronounced colitis induced by DSS, a phenotype associated with a higher intestinal production of IL-13." (PMID 33371444, 2020). "Therefore, the production of IL-4 and IL-13 in the colonic homogenate of rats was measured to study changes in the OXZ-induced colitis model." (PMID 31878303, 2019). "Next, we studied the role of IL-13 in a chronic DSS colitis in IL-13 KO mice 20,21." (PMID 31296924, 2019). "In addition, weight loss in mice with colitis that were treated with M2 macrophage exosomes (DSS + M0-exo; DSS + IL-13-exo; DSS + IL-10-exo; and DSS + IL-1β-exo) was also alleviated." (PMID 31749791, 2019). "Furthermore, cLP ILCs from T-betΔNCR+ILC DSS-colitis mice produced higher IL-13 and IL-5 after stimulation than ILCs from DSS-WT mice, whereas IL-17A and IFNγ production by ILCs were equivalent in both groups." (PMID 30356098, 2019). "Indeed, via cytokine Th2 production (IL-4, IL-5 and IL-13), they counterbalance the hyper reactive Th1 / Th17 response induced in colitis." (PMID 30592734, 2018). "Mouse studies identified an upregulation of IL-13 in colitis, which could be prevented by blocking the interaction of IL-13 with its signaling receptor." (PMID 28934123, 2017). "Mice infected with Hymenolepis diminuta and treated with the adult worm extract or treated with IL-4/IL-13–differentiated M2 macrophages have significantly reduced pathology in experimentally induced colitis; this protective effect is abrogated when IL-10 or macrophages are depleted." (PMID 27101372, 2016). "Administration of rSjcystatin significantly reduced inflammatory parameters and ameliorated the severity of the TNBS-induced colitis through decreasing IFNγ in three organs and lifting the level of IL-4, IL-13, IL-10, and TGF-β in the colon tissues, with uptrending Tregs in the MLN and LPMC." (PMID 26728323, 2016). "By augmenting the VDR function in invariant NKT cells using VD supplementation, IL-4 and IL-13 secretion could be up-regulated and therefore aggravate Th2-mediated colitis." (PMID 27620138, 2016). "The observed resistance to DSS-induced colitis in IL-25−/− mice led us to investigate whether this was related to defective IL-13 expression." (PMID 25937893, 2014).
colitis (continued). "In contrast, mice deficient in IL-13 are more susceptible to the colitis indicating the protection conferred by IL-25 deficiency is unlikely due to a lack of IL-13." (PMID 25937893, 2014). "On the other hand, our results from IL-13−/− mice on a C57BL/6 background are contrary to a recent study using IL-13−/− mice on a BALB/c background that showed reduced severity of DSS-induced colitis accompanied by decreased number of enterochromaffin cell and colonic serotonin content." (PMID 25937893, 2014). "We hypothesized that the IL-13-EC cell/5-HT axis is important in the pathogenesis of colitis whereby manipulation of the immune system to alter IL-13 production will modulate 5-HT production as well as the severity of colitis." (PMID 24015275, 2013). "In addition, there was a significant down-regulation of 5-HT production observed in the IL-13−/− mice in comparison to WT mice following DNBS-induced colitis." (PMID 24015275, 2013). "In addition, increasing colonic 5-HT content by administration of rmIL-13 or 5-HTP exacerbated severity of DSS colitis in IL-13−/− mice." (PMID 24015275, 2013). "IL-13−/− mice also exhibited reduced severity of DNBS-induced colitis." (PMID 24015275, 2013). "However, promising effects of IL-4/IL-13 dual antagonist were observed on murine colitis models." (PMID 38058517, 2023). "Whereas, rCsCP ameliorated the acute colitis might through activating innate immunity, downregulating the expression of pro-inflammatory factors (IL-12, IL-23r and IL-7), and promoting the production of anti-inflammatory factors (IL-10, IL-4 and IL-13)." (PMID 36084127, 2022). "Our current results indicated that rCsCP or CsCA might down-regulate the inflammatory responses of colitis mice via elevating Treg cells in both the spleens and MLNs, inducing the release of Th2 cytokines (IL-10, IL-4 and IL-13), and restraining the production of IL-1β and IL-2 cytokines in serum." (PMID 36084127, 2022). "Also, other investigators showed that increased STAT6 could play a significant role in colitis by affecting the IL-13 production, whereas a decrease in STAT6 could prevent apoptosis and disruption of cell membrane integrity." (PMID 35240996, 2022). "Furthermore, it is known that in DSS colitis colonic IL-13 expression is increased." (PMID 35563847, 2022). "Moreover, sustained CD4T cell-derived IL-13 activity protects mice from experimental colitis." (PMID 34581755, 2021). "Therefore, we believed that IL-13 could alleviate colitis by suppressing YAP function to enhance M2 macrophage polarization." (PMID 32676507, 2020). "In addition, IL-13 can cause epithelial barrier disturbance by increasing epithelial apoptosis and upregulating the tight junction protein claudin-2 expression in the OXZ-induced colitis model." (PMID 31878303, 2019). "Colitis was induced in IL-13 deficient (IL-13−/−) and wild-type (WT) mice with dextran sulfate sodium (DSS) and dinitrobenzene sulfonic acid (DNBS), as well as in IL-13−/− mice given recombinant mouse IL-13 (rmIL-13) and 5-hydroxytryptamine (5-HTP), the direct precursor of 5-HT." (PMID 24015275, 2013). "In conclusion, we suggest that Il-13 and TGFβ may play a role in H2O2-associated colitis." (PMID 23742011, 2013). "It has been shown that IL-13 signalling induces the production of TGF-β in macrophages, leading to colitis-induced intestinal fibrosis." (PMID 40332187, 2025). "The reduction in expression level of NLRP3 and its activity was further validated by measuring IL-1β, IL-13, MPO, and NO in colitis-induced mouse model." (PMID 37902927, 2024). "Reduced DAI, histology scores, and pro-inflammatory cytokines, with increased IL-13.Reduced inflammation, improved gut microbiota balance, and enriched metabolic pathways, indicating HB1628’s potential in mitigating colitis and modulating gut health." (PMID 39076514, 2024).
colitis (continued). "Similar trends were observed for IL-22, IL-13, LT-α and TNF-α, with small increases measured within the 2% DSS group and significantly higher systemic levels when the colitis worsens within the 3–5% DSS groups." (PMID 36672648, 2023). "In BALB/c background mice, CD90- ILC accounted for about a fifth to a third of cLP ILC, and we detected a substantial amount of IFNγ, IL-13 and IL-17A production by these cells in the context of DSS- or dysbiosis-elicited colitis." (PMID 37114052, 2023). "Overall, this panel identified IL-6, IL-22, IL-13, LT-α and TNF-α as upregulated inflammatory markers and CD40L as a downregulated marker of DSS-induced experimental acute murine colitis." (PMID 36672648, 2023). "These CD90- and CD90low ILC are a significant source of IFNγ, IL-13 and IL-17A upon dysbiosis and dextran sulphate sodium (DSS)-elicited colitis." (PMID 37114052, 2023). "It is likely that IL25 promotes colitis in an IL33 dependent manner on C57BL/6J, but promotes IL13 in BALB/c, which leads to the differences between the disparate strains." (PMID 35359953, 2022). "IL-13 secreted by ILC2 can induce epithelial cell SATA6 activation, which affects gut permeability and exacerbates experimental colitis, and STAT6 inhibition can reverse epithelial apoptosis and claudin-2 expression." (PMID 36032134, 2022). "Colonic tissues from DSS-induced colitis mice with Blastocystis ST4 colonization demonstrated increased expression of Th2 (IL-4, IL-5, and IL-13) cytokines relative to control mice." (PMID 35435504, 2022). "The present study confirmed and extended this effect by detecting a substantial reduction of IL-1α, IL-1β, IL-6, TNF-α, INF-γ, G-CSF, IL-13, GM-CSF, IL-3, MIP-1α, RANTES, and eotaxin cytokines in response to UTA77 treatment in both colitis models." (PMID 34497514, 2021). "Colitis increased amygdalar levels of Eotaxin, IL-13 and KC; whereas levels of IL-12p70 and VEGF were reduced in animals with colitis." (PMID 34916909, 2021). "As it was shown that IL-33 induces intestinal goblet cell differentiation indirectly through IL-13 production by ILC2s, we further assessed the impact of ILC2 transfer on goblet cells during DSS-induced colitis." (PMID 34335571, 2021). "Synergistically, Rg3-RGE + PT inhibited expression of NO, iNOS, COX-2, IL-1β, IL-6, IL-5, IL-13, and TNF-α in the DSS-induced colitis mice’s macrophage cells, plasma, and colon tissue." (PMID 33182623, 2020). "Increased levels of Flii also resulted in exacerbation of both Th1 and Th2 immune responses in colitis-induced mice with significantly greater levels of TNF-α, IFN-γ, IL-5 and IL-13 being observed." (PMID 31488864, 2019). "Compared with normal rats, the levels of many cytokines including IL-6, TNF-α, IL-17, IL-23, IL-1βand IFN-γ were increased, while IL-13, IL-10 and IL-4 were decreased in TNBS-induced colitis rats." (PMID 29113344, 2017). "This suggests that iNKT cells protected the mice from colitis, and consequently from the downstream development of colon tumors in the AOM-DSS model, through a mechanism that includes suppression of IL-13 production." (PMID 29375569, 2017). "For the anti-inflammatory cytokines, including IL-10, IL-13, TGF-β, a slight increase was observed in TNBS-induced colitis, which was consistent with previous work." (PMID 27544348, 2016). "In this study, exogenous IL-1β reduced expression of colonic Th2 cytokines (IL-4 and IL-13) and improved OXA-induced colitis, while exogenous IL-18 also reduced severity of the colitis but without affecting expression of Th2 cytokines." (PMID 27966619, 2016). "The Th1 transcription factor T-bet plays a critical role in the development of Th1-driven colitis due to the high expression levels of IFN-γ, while GATA3 is an essential master regulator of Th2 cells for the induction of IL-4, IL-5, and IL-13." (PMID 26347453, 2015).